ALB (albumin)
Diseases named in the same sentence as ALB in open-access papers (continued):
Sharing a sentence is not in itself a finding about the gene and the disease.
Sepsis (continued). "The present study revealed that early albumin administration was significantly associated with a higher risk of SA-AKI, which suggests that albumin may potentiate renal impairment in sepsis patients." (PMID 40841985, 2025). "The Controlling Nutritional Status (CONUT) score incorporates serum albumin, total lymphocyte count, and total cholesterol levels; this score has shown strong prognostic value for hospital mortality, risk of sepsis, and length of hospital stay among internal medicine patients." (PMID 41228403, 2025). "Therefore, we also conducted subgroup analysis by stratifying according to serum albumin levels, which revealed that AP patients with serum albumin ≤ 3.5g/L who received albumin infusions was associated with lower sepsis risk." (PMID 40773463, 2025). "Hematocrit (HCT) and albumin (ALB) levels are individually linked to sepsis." (PMID 41294166, 2025). "The decrease in serum albumin may be attributed to hepatic synthetic dysfunction and capillary leakage caused by sepsis-related endothelial damage, both of which can significantly reduce serum albumin levels." (PMID 40636366, 2025). "Furthermore, decreased albumin levels reduce the body’s antioxidant defenses, rendering patients more susceptible to oxidative stress–related damage associated with sepsis." (PMID 40901002, 2025). "Serum albumin (ALB) levels are also an independent risk factor for sepsis in children with IPD." (PMID 38898407, 2024). "Notably, this research pioneers the examination of the association between dynamic changes in serum albumin levels among adult sepsis patients and their adverse clinical outcomes." (PMID 39101009, 2024). "This study boasts several strengths: heretofore, no research has delineated the relationship between the spontaneous trajectory of albumin levels in ICU patients with sepsis and the risk of mortality, AKI, and fluid accumulation, among other adverse prognostic outcomes." (PMID 39101009, 2024). "Lactate levels, renal insufficiency, thrombocytopenia, pulmonary infections, UTI, and hyperthermia have been identified as risk factors for adverse sepsis outcomes, whereas higher levels of plasma albumin and IgG may provide protection." (PMID 38671376, 2024). "The main objective was to evaluate the distribution of mortality between sepsis and septic shock patients and identify contributing factors (e.g., serum lactate, lactate/albumin ratio, C-reactive protein, and platelet levels) associated with 30-day mortality among COVID-19 patients." (PMID 38576552, 2024). "Second, from a physiological perspective, albumin is synthesized in the liver, and the impairment of liver function in sepsis may cause a deficiency in albumin synthesis." (PMID 38826606, 2024). "Our research findings indicated that decreased levels of albumin upon admission to ICU were associated with an unfavorable prognosis in sepsis-induced ARDS, thereby further providing evidence for a correlation between lower albumin levels and poorer clinical outcomes in infectious diseases." (PMID 39686985, 2024). "Temperature (OR 3.80, 95% CI 1.62–8.87; P = 0.0021), Partial Pressure of Oxygen in Arterial Blood (PaO2) (OR 0.99, 95% CI 0.98-1.00; P = 0.0266), and albumin (OR 0.89, 95% CI 0.80–0.99; P = 0.0329) were found to be independent risk factors for sepsis in children with IPD." (PMID 38898407, 2024). "Serum albumin levels are closely associated with sepsis severity and prognosis." (PMID 39564496, 2024). "Albumin is an indicator of inflammation and systemic nutritional status, and studies have shown that albumin is associated with the prognosis of patients with sepsis." (PMID 37194715, 2023). "Therefore, supplementing albumin in patients with gastrointestinal perforation and low albumin levels can be beneficial in reducing the risk of sepsis." (PMID 37809261, 2023).
Sepsis (continued). "In addition, lower ALB is a risk factor for elderly people with bacterial infections, and early infusion of albumin seems to reduce the mortality of patients with sepsis." (PMID 37626308, 2023). "Low albumin levels are associated with high sepsis severity scores, high circulating levels of tumour necrosis factor (TNF), interleukin (IL)-1 and IL-6, and the presence of microcirculatory dysfunction seen in capillary leak syndrome, which is responsible for the poor prognosis of infections." (PMID 37240554, 2023). "A serum albumin concentration below 20 g/L is associated with decreased survival in a variety of diseases, including protein-losing enteropathy and nephropathy, liver failure, sepsis, heart failure, and hemorrhage." (PMID 37342623, 2023). "Studies indicate that serum albumin is an independent prognostic risk factor for sepsis patients." (PMID 37817258, 2023). "In our previous study, we found that reduced LCAT activity due to increased oxidative stress is a cause of reduced cholesterol levels, and albumin is a transport carrier of cholesterol and other molecules, likely affecting the fluctuation in fatty acid and outcomes in sepsis." (PMID 36832250, 2023). "Serum albumin levels are associated with the prognosis of pneumonia, severe sepsis, and bacteremia." (PMID 37065302, 2023). "Moreover, decreased serum albumin levels in sepsis are associated with capillary leak syndrome caused by increased vascular permeability." (PMID 37085944, 2023). "Therefore, we assessed the relationship between ferritin/albumin and the 28-day all-cause mortality rate in patients with sepsis based on the MIMIC-IV database." (PMID 37817258, 2023). "In contrast to VEGF, the decrease in serum albumin levels in sepsis causes tissue edema." (PMID 37085944, 2023). "Excess albumin decreases platelet aggregation in plasma, and albumin deficiency increases platelet aggregation, which may be associated with poor prognosis in sepsis and chronic diseases." (PMID 37109621, 2023). "However, low serum albumin levels have been associated with an increased risk of death in patients with severe sepsis." (PMID 37626427, 2023). "Furthermore, the daily changes of albumin were significantly linked with mortality during the ICU stay in sepsis patients." (PMID 36528689, 2022). "In several sepsis studies, the serum albumin level was associated with increased mortality." (PMID 36498805, 2022). "In addition to mortality, albumin levels have also been revealed to be associated with morbidities, such as sepsis and major infections." (PMID 36110400, 2022). "Therefore, our study aimed to analyze the association between ALB levels and mortality in sepsis patients with AKI undergoing CRRT." (PMID 35109818, 2022). "Albumin, as the main protein which can balance capillary membrane permeability and plasma osmotic pressure, was identified to be associated with occurrence and clinical outcomes in sepsis." (PMID 36528689, 2022). "Albumin (ALB) levels are negatively associated with mortality in patients with sepsis." (PMID 35109818, 2022). "Several studies evaluated the albumin quantity and the albumin redox state associated with the oxidative stress level in various research areas of medicine, especially in the context of liver cirrhosis, acute kidney injury and sepsis." (PMID 35842435, 2022). "In a randomized controlled trial, administration of albumin may have decreased the risk of death, which indicated it was associated with albumin with the prognostics of sepsis patients." (PMID 36033731, 2022). "Although many factors could be the cause of low albumin levels including liver disease, sepsis, and nephrotic syndrome, all complications in this study were caused by chronic nausea syndrome or obstructive bowl syndrome." (PMID 33730334, 2021).
Sepsis (continued). "Edema in MHD patients is multifactorial and may be due to low albumin, excessive fluid intake, poor cardiac status, inadequate hemodialysis due to intradialytic hypotension, sepsis, poor quality of dialysis or other causes." (PMID 34765364, 2021). "Monitoring of C-reactive protein/albumin level in a patient admitted to intensive care unit could be useful for stratifying patients with a high risk of developing sepsis." (PMID 35199783, 2021). "Low serum albumin was an independent risk factor for sepsis in the current study." (PMID 33481913, 2021). "As we know, albumin is similarly associated with outcomes in sepsis and septic shock; randomized controlled trials in this field could be a start." (PMID 34921151, 2021). "Though low albumin levels may be induced by liver or kidney disease, it is still not clear how low the level of serum albumin increases significantly the death risk of sepsis patients." (PMID 34839820, 2021). "Currently, although ischemia-modified albumin has been mainly used for diagnostic and prognostic purposes relating to acute coronary syndrome, elevated levels have also been linked to a poor outcome of patients experiencing acute chest pain and severe sepsis." (PMID 34604356, 2021). "In such a case the association between them could be explained by a sepsis being a common cause affecting the albumin concentration and volume of distribution of meropenem." (PMID 32301057, 2020). "Lnc‐MALAT1 was positively correlated with Scr (r = .254, P < .001), CRP (r = .494, P < .001), TNF‐α (r = .387, P < .001), IL‐1β (r = .330, P < .001), IL‐6 (r = .431, P < .001), and IL‐8 (r = .420, P < .001), while negatively associated with albumin (r = −.153, P = .033) in sepsis patients." (PMID 32309886, 2020). "Univariate analysis showed that post-PCNL sepsis was associated with the female, lower albumin, higher globulin, lower albumin globulin ratio (AGR < 1.5), preoperative fever, leukocytosis (WBC ≥ 10,000 cells/μL), positive urine culture, leukocyturia (≥50 cells/μL) and positive urine nitrite." (PMID 32655994, 2020). "BMI has been shown to be a single clinical variable influencing surgical outcome, and the serum albumin level is a well-known factor predicting the risk of infectious complications and sepsis, and recent papers underlined the role of immune stimulating diet or enteral nutrition prior to surgery." (PMID 31191642, 2019). "We were able to confirm these results; a sepsis-induced reduction of CSE expression was associated with kidney barrier dysfunction (indicated by the increased albumin extravasation) and thus contributed to the reduced glomerular filtration, as evinced in the impaired CrCl." (PMID 30343340, 2018). "In a meta-analysis of 17 randomized controlled trials assessing the effect of albumin as a resuscitation fluid for patients with sepsis, the use of albumin-containing solutions was associated with lower mortality compared with other fluid resuscitation regimens." (PMID 29927987, 2018). "Furthermore, multiple logistic regression analyses identified the following factors as independent risk factors for sepsis: lower albumin and NRS-2002 score on admission." (PMID 26938553, 2016). "We found that an admission albumin less than 3.5 g/dL and an ED triage diastolic blood pressure less than 52 mmHg were independently associated with the development of organ failure or shock in sepsis within 96 h of ED presentation." (PMID 26908009, 2016). "Moreover it shows, for the first time, that among factors that can affect drug pharmacokinetics during the early phases of sepsis, urinary loss of both free and albumin-bound antimicrobials should be considered." (PMID 27846855, 2016). "In a murine cecal ligation/perforation (CLP) model of sepsis, pulmonary microvascular Evans blue (EB)-labeled albumin leak was associated with significant pulmonary cell death in vivo as visualized by intravital videomicroscopy (IVVM) and confirmed by histology." (PMID 24516666, 2014).
Sepsis (continued). "Whether albumin is associated with reduced mortality in the resuscitation of severe sepsis and septic shock compared with crystalloid is a matter of debate." (PMID 25499187, 2014). "Furthermore, a large meta-analysis showing resuscitation with albumin solutions in sepsis was associated with lower mortality." (PMID 25180196, 2014). "Meanwhile, the results from the SAFE study and a subsequent Meta-analysis have shown that albumin as a resuscitation fluid for patients with sepsis may significantly reduce the risk of death." (PMID 25474401, 2014). "Not only did these studies show albumin did not increase mortality, but importantly, the SAFE study revealed in its subgroup analysis the use of albumin to be associated with decreased 28-day mortality in severe sepsis, suggesting a potential benefit of albumin use in this population in particular." (PMID 25625012, 2014). "In a large controlled, randomized trial, the administration of albumin may have decreased the risk of death in patients with severe sepsis compared with saline." (PMID 23414610, 2013). "In addition, serum ALB level has been identified as an independent risk factor for increased short- and long-term mortality in patients with acute conditions such as trauma, cardiogenic shock, and sepsis." (PMID 40438354, 2025). "Furthermore, prior observational studies have indicated that serum albumin may serve as a potential risk factor for mortality among patients with sepsis." (PMID 40612738, 2025). "Thus, the objective of this study was to investigate whether early administration of serum albumin infusion in the AP patients admitted to the ICU reduces the risk of sepsis, providing valuable insights for guiding the treatment strategy for AP patients." (PMID 40773463, 2025). "In addition, early serum ALB supplementation may reduce the in-hospital mortality associated with sepsis." (PMID 40357038, 2025). "In addition, low serum albumin leels were a risk factor for liver cirrhosis patients with sepsis, correction of low serum albumin leels may improve the prognosis of patients with this kind of ending." (PMID 39039452, 2024). "Furthermore, albumin is strongly associated with prognosis in patients with sepsis." (PMID 39272772, 2024). "Therefore, the mouse model incorporating this Se/Mn/albumin nanomaterial that is recommended for in vivo testing must consider macrophages in the M1 state that are dominant in severe and critical lung diseases that cause sepsis such as COVID-19." (PMID 39459897, 2024). "This indicates that maintaining albumin levels might support the gut–liver axis in sepsis, potentially reducing bacterial translocation and associated complications; however, direct evidence in the context of sepsis is limited." (PMID 38139434, 2023). "Patients with biliary tract cancers have more surgical trauma and albumin loss following radical surgery; if hypoproteinemia continues over an extended period of time after the operation, it will lead to an increased adverse prognosis, such as bile leakage, sepsis, or even death." (PMID 38375202, 2023). "In addition, the association could be due to reverse causation in some circumstances such as severe sepsis or systemic inflammation in COVID that can lead to leakage of albumin and vitamin D binding protein and consequently lead to low levels of 25(OH)D." (PMID 35276834, 2022). "Furthermore, the low serum albumin level in the acute phase of sepsis may be due to the inhibition of the albumin gene caused by TNF-α overexpression during inflammation." (PMID 35453552, 2022). "This may explain why albumin is closely associated with sepsis prognosis." (PMID 35990041, 2022). "A moderate correlation with u-TP, u-albumin and se-creatinine suggest that elevated u-actin levels could be the consequence of severe glomerular injury potentially caused by sepsis-related systemic cellular damage with an excessive release of free extracellular actin." (PMID 34310652, 2021).
Sepsis (continued). "First, we lacked data regarding vital signs from each patient, such as serum albumin, blood pressure, urine volume, and disease severity, such as the amount of blood loss in the “bleeding” group and the sequential organ failure assessment score in “sepsis” patients." (PMID 31878921, 2019). "Therefore, if sepsis causes relatively low albumin and high SHBG concentrations, septic patients could have high total but low bioavailable estradiol levels." (PMID 27765072, 2016). "Initial serum albumin <3.5 mg/dL (OR 4.82; 95 % CI 2.40–9.69; p < 0.01) and a diastolic blood pressure <52 mmHg at ED triage (OR 4.59; 95 % CI 1.57–13.39; p < 0.01) were independently associated with disease progression to severe sepsis or shock within 96 h of ED presentation." (PMID 26908009, 2016). "Therefore, cirrhotic patients at high risk of circulatory dysfunction during paracentesis should receive albumin or an alternative plasma expander, and cirrhotic patients with sepsis or infection at high risk of renal impairment or death should receive albumin." (PMID 24222902, 2013). "The highest PCT concentrations and composite index values were observed in the sepsis group, while mixed and septic patients demonstrated the lowest ALB levels." (PMID 41598762, 2026). "The C-reactive protein (CRP)-albumin-lymphocyte (CALLY) index is a novel composite biomarker for sepsis." (PMID 41835671, 2026). "The HALP score represents a convenient and potentially useful tool for prognostic assessment in sepsis, combining hemoglobin, albumin, lymphocyte, and platelet levels into a single, easily obtainable index." (PMID 41602009, 2026). "Nevertheless, the specific relationship between the hematocrit-albumin gap (HAG) and susceptibility to sepsis remains underexplored." (PMID 42078461, 2026). "Prior research has identified hematocrit and albumin levels as potential prognostic indicators for sepsis." (PMID 42078461, 2026). "This systematic review and meta-analysis evaluated the effectiveness of human albumin solution compared with control fluids across four patient-centred outcomes in adults with sepsis or septic shock." (PMID 42291862, 2026). "The aim of this study is to evaluate the prognostic value of the lactate to albumin ratio (LAR) in predicting morbidity, acute kidney injury associated with sepsis (SA-AKI) and mortality in sepsis patients." (PMID 41517778, 2026). "Liu's team also revealed an independent correlation between APAR (alkaline phosphatase-to-albumin ratio) and sepsis prognosis in a retrospective study." (PMID 41601745, 2026). "In the CRRT group, EC injury indicators correlated with albumin and lactic acid at sepsis diagnosis." (PMID 41916904, 2026). "Wiedermann’s study found that albumin insufficiency, which plays a crucial role in antimicrobial defense and repair, can induce wound healing issues, wound infection, sepsis, and septic shock alone." (PMID 41303773, 2025). "Considering the fact that both PCT and serum albumin (ALB) are closely related to infection and inflammation, the PCT-to-ALB ratio (PAR) has been found to strongly correlate with mortality in adults with sepsis-induced acute kidney injury." (PMID 40351994, 2025). "The search terms included “pediatric sepsis,” “fluid therapy,” “vasopressors”, “shock management,”, “diuretics”, “hypervolemia”, “tolerance fluids”, “albumin”, and “fluid creep,” combined using Boolean operators." (PMID 39944316, 2025). "This study aimed to investigate the association between the serum albumin-to-creatinine ratio (ACR) and the prognosis of sepsis." (PMID 40978746, 2025). "This suggests to clinicians that maintaining ALI within an appropriate range for sepsis patients (for example, through managing weight, supplementing albumin, and administering anti-inflammatory therapies) is crucial for prognosis." (PMID 40438347, 2025). "Albumin decreases in serum levels during inflammation, especially in conditions like acute respiratory failure and sepsis." (PMID 40130722, 2025).